CCL21 (C-C motif chemokine ligand 21)
Diseases named in the same sentence as CCL21 in open-access papers (continued):
Sharing a sentence is not in itself a finding about the gene and the disease.
tumor (continued). "We hypothesize that the CCL21-DC tumor Ag vaccine mediated specific systemic immunity will benefit patients who have limited CD8 T cell infiltration of their tumors and or limited expression of tumor PD-L1." (PMID 32570793, 2020). "Anti-PD-1 or CCL21-DC tumor Ag vaccine monotherapy reduced tumor burden without tumor eradication." (PMID 33167311, 2020). "A possible explanation for this paradoxical result is that CCL21 itself is not sufficient to inhibit tumor cell migration, and additional factors may be required for CCL21 to regulate PANC-1 cell migration." (PMID 29687228, 2020). "Thus, the tumor microenvironment factors do not inhibit the responsiveness of luminal-B cells to chemotactic cues mediated through the CCR7/CCL21 axis." (PMID 32340161, 2020). "While tumors treated with T-cells pre-cultured on uncoated substrates continuously grew in size over time, the tumors treated with T-cells cultured on CCL21 + ICAM1 substrates displayed almost no increase in tumor size, throughout the follow-up period (14 days)." (PMID 29942308, 2018). "EGF may also be involved in reducing docetaxel efficacy in cancer cells; however, a number of other molecules including IL-6, TGFβ, CXCL12, CCL21, VEGF, among others secreted by activated lymphatics are known contributors to drug resistance and these interactions may be tumor cell specific." (PMID 29976154, 2018). "In addition, the tumor samples were stained for CCR7, the receptor of CCL21." (PMID 27369431, 2016). "Further studies showed that the full potency of CCL21-mediated anti-tumor response required the induction of IFN-γ, MIG/CXCL9 and IP-10/CXCL10 in concert, as neutralization or depletion of any one of these cytokines led to a decrease in the frequency of CXCR3+ve T cells and CD11c+ve DC in the tumor." (PMID 24810425, 2014). "In addition to induction of a migratory phenotype and directing metastasizing tumor cells to regional lymph nodes the CCR7/CCL21 axis may also foster tumor metastasis by preventing anoikis in cancer cells and up-regulation of matrix metalloproteinase-9 (MMP9)." (PMID 23667660, 2013). "The regional lymph nodes from Ndst1f/fProx-/CreERT2 wildtype littermates showed large areas of CCL21 positive cells that were found to tightly localize to areas of pan-keratin positive tumor metastases (compare pan-keratin and CCL21 photomicrographs from a representative Cre negative animal)." (PMID 21172016, 2010). "The rationale for utilizing CCL21-DC as opposed to direct injection of AdCCL21 or recombinant CCL21 is derived from pre-clinical murine studies in which CCL21 administered as a recombinant protein showed anti-tumor properties only at very high doses." (PMID 18644162, 2008). "We anticipate that clinical grade CCL21-DC may be an effective immunotherapeutic approach in the treatment of NSCLC, utilizing the in vivo tumor as the source of TAA, and thus eliminating the need for ex vivo priming with tumor antigens." (PMID 18644162, 2008). "Besides, considering the present study did not elucidate specific regulatory mechanisms for CCL21 affecting NF-κB pathway to regulate neutrophils as well as the potential effects of CCL21 on tumor cells, basic studies based on in vivo and in vitro experiments are needed in the future." (PMID 38367070, 2024). "Since the predominant Treg subset in human and mouse tumors is the thymus-derived naturally occurring Treg, a lack of CCL21-Ser expression in the Ccl21a-KO thymus may cause intrinsic dysfunction of naturally occurring Tregs and accelerated CD8+ T-mediated tumor rejection." (PMID 37664721, 2023). "Mediators of tumor-associated immune suppression include, but are not limited to, the recruitment of immunosuppressive cells (e.g., MDSC, Treg), the expression of immune checkpoint proteins, production of TGF-β or CCL21, and induction of cell death in anti-tumor effector cells." (PMID 33923319, 2021).
tumor (continued). "In addition to a reduction in angiogenesis, intratumoral injection of a recombinant CC chemokine, CCL21, induced tumor regression in immunocompetent mice, but not immunosuppressed mice, suggesting that T cell immunity was required for the antitumor effect of CCL21." (PMID 24971349, 2014). "The CXCR4/SDF-1 and chemokine (C-C motif) receptor 7/chemokine (C-C motif) ligand 21 (CCR7/CCL21) interactions may play key roles in accentuating the adhesion of tumor cells as the lung endothelium expresses a high level of SDF-1 and CCL21 to complement tumor cell expression of CXCR4 and CCR7." (PMID 22295241, 2012). "We have hypothesized that intratumoral injection of CCL21-gene modified DC (CCL21-DC) will stimulate specific immune responses without excluding patients on the basis of HLA phenotype or absence of a particular tumor antigen." (PMID 18644162, 2008). "Vascular normalization also occurred in CCL21 knockdown tumors without TMZ treatment, without reducing tumor size." (PMID 37314567, 2023). "In the tumor samples, EWS cells were negative for CCL21 and CCR7, while infiltrating immune cells did show expression of both CCL21 and CCR7." (PMID 27369431, 2016). "In this process, the absence of CAF_CCL21 also impairs complement-dependent CR2 activation of B_CD74, while the dysfunction of B_CD74 weakens CD6-dependent activation of CD8+ T cells, thereby attenuating their involvement in anti-tumor immunity." (PMID 38505619, 2024). "Moreover, CCL21-Ser expression was undetectable in tumor tissues, suggesting the contribution of host-derived CCL21-Ser and CCR7 on nontumor cells to B16–F10 tumor growth." (PMID 37664721, 2023). "The reason may well be that CCL19 and CCL21 function better in the tumor progression rather than the tumorigenesis process of HCC, and DEN/CCl4-induced tumor models are not strongly consistent due to individual differences among mice and the sample sizes." (PMID 35673582, 2022). "Deletion of lymphatic endothelial Ndst1 resulted in a decreased xenograft tumor cell metastases to lymph nodes and oxazolone induced lymph node homing of DCs possibly via defective CCL21 oligomerization and/or promotion of CCR7-CCL21 interaction rather than anchoring to the matrix." (PMID 33717158, 2021). "Therefore, the protein expression levels and localization of CCL21 were determined in EWS patient samples using IHC and demonstrated that CCL21 expression was restricted to tumor infiltrating immune cells and that it was not present in EWS cells." (PMID 27369431, 2016). "Therefore, the upregulation of CCL21 and ANGPTL4 in this trial might favor more aggressive disease and not necessarily benefit tumor suppression." (PMID 37688629, 2023). "The fact that PAK4 KO cells do not secrete any CCL21 suggests that, although another cell type is responsible for the secretion of this chemokine, the absence of PAK4 might contribute to increase its concentration in the tumor microenvironment." (PMID 36588582, 2022).
cancer (146 papers, 2007 to 2026). A tumor composed of atypical neoplastic, often pleomorphic cells that invade other tissues. "Several CC chemokines, such as CCL1, CCL2, CCL5, CCL18, and CCL21, have been implicated in cancer, exhibiting both pro- and anti-tumorigenic roles." (PMID 39409924, 2024). "Of the two ligands of CCR7, CCL19, and CCL21, only CCL21 is associated with metastasis, contributing to lymphatic metastasis in pancreatic, lung, breast, and other cancers via ERK signaling." (PMID 39114657, 2024). "Recently, the CC motif chemokine ligand 21 (CCL21) has been widely linked to cancer cell invasion and migration." (PMID 36829431, 2023). "CCR7 (C-C Motif Chemokine Receptor 7), a receptor of cytokines CCL19 and CCL21, is implicated in the homing of T cells in lymph nodes, and it has mostly been studied with regard to its proangiogenic effect on cancer cells through an increase in VEGF levels." (PMID 38153746, 2023). "Concordant to our data, recently it has been pointed out that CCL21/CCR7 is linked with cancer recurrence, smoking, and poor prognosis in HN cancer." (PMID 32961854, 2020). "Induction of CCL21 was found in tertiary lymphoid structures which participated in development of inflammation-associated cancer in spontaneous gastric tumorigenesis model." (PMID 31523177, 2019). "Moreover, we observe a closer association of invasive than of non-invasive cancer cells with the lymphatic networks, which can be inhibited by blocking of CCL21." (PMID 41566883, 2026). "Furthermore, CCL21 has been widely reported to be associated with the metastasis of cancer cells." (PMID 36829431, 2023). "The genetic characterization of 12 chemokines in TLS, particularly CCL19, CCL21, and CXCL13, has been linked to increased survival in patients with BC, CRC, and other cancers." (PMID 40038799, 2025). "Heatmap and functional annotation indicated that several significantly upregulated genes (CCL21, H2‐Eb2, Pax5, CD19, CD22, etc.)were associated with anti‐cancer immunity." (PMID 41306557, 2025). "CCL21, a secondary lymphoid tissue chemokine, is expressed by HEVs, lymphatic endothelial cells, and cancer cells." (PMID 39840050, 2024). "Tumor necrosis factor -α, a proinflammatory cytokine, can increase CCR7 expression in cancer cells, promoting the production of CCL21 in human lymphatic endothelial cells." (PMID 39114657, 2024). "In BCa, the CCR7/CCL21 axis increases proliferation, invasion, and lymph node metastasis and decreases the apoptosis of cancer cells." (PMID 39409924, 2024). "In an orthotopic PDAC animal model known to develop cancer-associated pain, administration of CXCL10- or CCL21-neutralizing antibodies significantly reduced the extent of nerve fiber hypertrophy and, consequently, the development of cancer-associated pain." (PMID 37834436, 2023). "CCL21 produced by lymphatic endothelial cells generates a concentration gradient that induces migration of cancer cells to the lymph nodes (LNs) in a CCR7-dependent manner." (PMID 37664721, 2023). "According to several experimental studies, cancer cells interact with the chemokine (C-C motif) ligand 21 (CCL21)/chemokine (C-C motif) receptor type 7 (CCR7)." (PMID 37635248, 2023). "Prior to injection of B16F10 cancer cells, lungs from E2-/- mice initially expressed significantly less CCL21 transcript compared to B6 mice." (PMID 37426658, 2023). "Consistent with this, treatment of E0771-MOCK with CS inhibited CCL21-induced T-cell migration in vitro in trans-cancer migration assays." (PMID 35094065, 2022). "Recent studies performed on cancer revealed the essential roles of Ccl21-Ccr7 in neoangiogenesis, proliferation, activation, retention, and accumulation of T-cells at the persistent inflammation sites." (PMID 35180880, 2022). "Expression and secretion of CCL21 by human MSCs can facilitate chemotactic attraction to cancer cell lines." (PMID 35103937, 2022).
cancer (continued). "Simultaneously, VEGF-C also enhanced the expression of Ccl21 in the lymphatic endothelium to promote the entry of Ccr7+ cancer cells into the SLN." (PMID 36266717, 2022). "Accordingly, CCL21 is a base for cancer immunotherapy since it can chemoattract T-lymphocytes and DCs." (PMID 36037155, 2022). "Remarkably, there are several other types of reported studies signifying that each time cancer cells express CCL21 and increase the level of white blood cell recruitment in a specific subpopulation of T–cells CD8 positive and dendritic cells." (PMID 35874608, 2022). "Antagonizing these receptors and/or ligands provided novel platforms for cancer therapeutics: CCR7/CCL21 for lymph node metastases, and CXCR4/CXCL12 for lung, liver, bone marrow and brain metastases." (PMID 35203305, 2022). "The results demonstrated a decrease in survival rate and metastasization of cancer cells in the presence of CCL21/IL1β, and IC50 of CCL21 on MCF7 cells was less than that of non-recombinant protein." (PMID 36037155, 2022). "CCR7 receptor activity is essential for immune cell entry into lymphatic vessels, and it binds to CCL21, preferentially expressed in secondary lymphoid tissues that drain many cancers." (PMID 33390169, 2021). "Partially consistent with our findings, the secretion of CCL21 has been previously reported in a variety of cancers including GC." (PMID 34001131, 2021). "Existing literature has emphasized the chemokine CCL21 as a therapeutic biomarker for solid human cancers while highlighting its upregulation in GC, suggesting its significance as a gene of GC." (PMID 34001131, 2021). "Of the two CCR7 ligands, CCL21 has more robust activities in dendritic cell migration and is the most investigated in cancer." (PMID 34298676, 2021). "These 8 genes (SPP1, TTK, MELK, FOXM1, LYN, ARRB2, COL6A3, and CCL21) were further validated in more numbers of cancer tissue samples by quantitative real-time PCR (qRT-PCR)." (PMID 33829064, 2021). "The present study not only highlights the important role of bone marrow-derived hMSCs’ CD9-mediated CCL21 regulation in cancer bone metastasis but also suggests a new distinct pharmaceutical strategy for prevention or/and therapy of cancer metastasis." (PMID 33572290, 2021). "The interactive analysis tool was applied to confirm the expression level of the eight DEGs (SPP1, TTK, MELK, FOXM1, LYN, ARRB2, COL6A3, and CCL21) in cancer and normal tissues." (PMID 33829064, 2021). "These cancer hybrid cells responded to the chemokine CCL21 with an increased migratory activity, whereas the parental cells did not." (PMID 34503305, 2021). "Our data demonstrate that the CCL21-DC tumor Ag vaccine has the means to overcome this limitation for long-term cancer-free survival and provide justification for evaluation for clinical translation." (PMID 32570793, 2020). "The CCR7 ligand CCL21 is expressed selectively in high endothelial venules at the entry point into the lymph node and promotes cancer progression." (PMID 32704070, 2020). "It suggested that the CCL21 secreted by TNF-α-treated HLEC is involved in the process of cancer metastasis." (PMID 33158173, 2020). "Encouragingly, many studies correlating with the effects of CCL2, CCL11, and CCL21 on anti-cancer properties focus on their relationships with T cell functions." (PMID 31754081, 2019). "The results demonstrated decreased survival and anti-metastatic of cancer cells in the presence of CCL21 recombinant protein." (PMID 29276695, 2018). "Chemokine (C-C motif) ligand 21 (CCL21), a ligand of the chemokine (C-C motif) receptor 7, has recently been identified as an immuno-based anti-cancer molecule for its dendritic cells and T lymphocytes chemoattractant function." (PMID 27783999, 2017). "As shown here, higher PDPN expression is due to hypoxia under which condition, the addition of CCL21 is required to help the CAF/cancer cell interaction." (PMID 28416768, 2017).
cancer (continued). "C-C chemokine receptor 7 (CCR7) interacts with its ligand, chemokine ligand 21(CCL21), to mediate metastasis in some cancer cells lines." (PMID 27505247, 2016). "In conclusion, we demonstrated that CCL21 is able to promote chemoresistance and cancer stem cell properties in HCT116 cells and Snail plays an important role during this process." (PMID 27057280, 2016). "Collectively, our results revealed that CCL21 can induce cancer stem cell properties and upregulation of Bmi-1, Nanog, and Oct-4 in HCT116 cells." (PMID 27057280, 2016). "The CCR7-CCL19/CCL21 axis is simultaneously involved in cancer cell dissemination and metastasis formation as well as in adaptive immune cell homing to lymphoid organs." (PMID 28036019, 2016). "Our results suggested that Snail was crucial for CCL21-mediated chemoresistance and cancer stem cell property in CRC cells." (PMID 27057280, 2016). "CCL21 has been shown to be responsible for mediating metastasis, especially lymph node metastasis, in certain cancer cells lines." (PMID 27505247, 2016). "In our study, the results show that Snail played a vital role in CCL21 promoted chemoresistance and cancer stem cell properties." (PMID 27057280, 2016). "Molecules like chemokine CCL21 are involved in the metastasis of cancers not only via mediating the migration and invasion of cancer cells into tissues but also providing the required supportive microenvironments." (PMID 25798926, 2015). "CCL21 is critical in mediating activated DCs and T cells to lymph system niches and triggering subsequent immune response to foreign antigen, therefore providing the rationale for CCL21 based cancer immunotherapy." (PMID 24810425, 2014). "CCL21 priority ranking is 13 amongst the list of twenty National Cancer Institute ranked biological agents with high potential for use in cancer therapy." (PMID 24810425, 2014). "The ability of CCL21 to chemoattract DC and T lymphocytes forms the rationale for CCL21-based cancer immunotherapy." (PMID 24810425, 2014). "Collaboration among immunologists, material scientists and physicians will create future generations of CCL21 based anti-cancer immunotherapy." (PMID 24810425, 2014). "The results suggest that CCL21 triggers the activation of CCR7 signaling through CCL21 secreted from cancer cells in an autocrine manner." (PMID 22251626, 2012). "Recently, CCL21 was shown to be secreted not only by lymphatic endothelial cells (LECs), but also by the cancer cells themselves." (PMID 22251626, 2012). "This process is aided by the LECs themselves, which secrete chemokines such as CCL21 that induce chemotaxis in antigen-presenting cells and some cancer cells." (PMID 22505936, 2012). "Normally, CCR7 activity is regulated by CCL19 and CCL21, which is secreted by cancer cells themselves and allows cancer cells to migrate to the lymphoid tissues." (PMID 22251626, 2012). "Herein, we report the discovery of a central role played by unique glycans in regulating chemokine-mediated carcinoma cell traffic in vivo and in vitro, and we focus on CCL21 as a prototypical chemokine regulated by this novel process." (PMID 21172016, 2010). "CCL21 has also shown anti-angiogenic activities in mice, thus strengthening its immunotherapeutic potential in cancer." (PMID 18644162, 2008). "We speculate that RANBP17 may suppress stromal CXCL13, CCL19 and CCL21 through exosome‐mediated mechanisms by reprogramming the cargo of cancer‐derived exosomes to include regulatory RNAs and proteins." (PMID 41397929, 2025). "Based on the single‐cell sequencing derived from NPC clinical samples, RANBP17 is expressed in EBV‐associated NPC cells, KCNJ10 is detectable in myeloid cells, and CXCR5 is dormantly expressed by B cells, while cancer‐associated fibroblasts mainly express CCL19 and CCL21." (PMID 41397929, 2025). "In support of our hypothesis, we found significantly higher numbers of FRC-like fibroblasts expressing CCL19 and CCL21 in immune-hot HPV+ve cancers." (PMID 39757146, 2025).